SUFU (SUFU negative regulator of hedgehog signaling)
Diseases named in the same sentence as SUFU in open-access papers (continued):
Sharing a sentence is not in itself a finding about the gene and the disease.
medulloblastoma (continued). "These genes have not (yet) been implemented in routine genetic testing strategies for patients with the suspected diagnosis of Gorlin syndrome and might (partially) close the diagnostic gap in young children with SHH-activated medulloblastomas lacking germline PTCH1 or SUFU mutations." (PMID 34888241, 2021). "To date, the majority of pediatric brain tumor GEMMs are SHH-activated medulloblastoma, which are generated by modifying SHH signaling genes, such as PTCH, SMO, or SUFU." (PMID 33869004, 2021). "SHH-activated medulloblastoma is highly heterogeneous and many key molecules in the SHH signaling pathway such as SUFU, smoothened (SMO), PTCH1, GLI1 and GLI2 have been dysregulated in this subgroup." (PMID 33869004, 2021). "The initial medulloblastoma mouse models followed the discovery of frequent mutations of the patched (PTCH) gene (i.e. the sonic hedgehog (SHH) receptor) and downstream signalling factors (SUFU, SMO and GLI) in medulloblastoma derived from the external granular layer." (PMID 39324445, 2024). "As a first approach we triggered SMO-independent GLI activation in human medulloblastoma cells (DAOY) by RNAi mediated knockdown of SUFU, a critical negative GLI regulator acting downstream of SMO." (PMID 26784250, 2016). "A second subtype, not completely separated from all other medulloblastomas in their cluster analyses, was found to be enriched in mutations in either PTCH1 or SUFU and was characterized by activation of the SHH signaling pathway." (PMID 18769486, 2008). "However, sonidegib did not affect the proliferation of medulloblastoma with MYCN amplification or SUFU deletion." (PMID 35163655, 2022). "Importantly and in line with our DYRK1B RNAi data, DYRKi treatment of SAG-treated SUFU-positive (WT MB +SAG) and untreated SUFU-depleted (ΔSufu MB) human medulloblastoma cells prevented GLI1 mRNA expression at comparable IC50 concentrations of 1.16 μM and 1.04 μM, respectively." (PMID 26784250, 2016).
Gorlin syndrome (37 papers, 2011 to 2026). "BACKGROUND: Individuals meeting clinical diagnostic criteria for Gorlin syndrome typically harbor germline pathogenic variants in PTCH1 or SUFU." (PMID 41888819, 2026). "Genes such as SUFU, which harboured an lpVUS in one of the patients diagnosed at 22 years of age, is known for its association with Gorlin syndrome, while ASXL1 and NOTCH2, identified in another patient, have been implicated in familial CRC." (PMID 40627234, 2025). "Germline inactivation of one copy of the Hh receptor Patched 1 (PTCH1) gene and, more rarely, of PTCH2, or of Suppressor of Fused (SUFU), followed by the somatic loss of the second allele results in Gorlin syndrome that are frequently observed in BCC patients." (PMID 35804983, 2022). "Patients with SUFU mutations have a 20-fold higher risk of developing medulloblastoma (33%) than patients with PTCH1 mutations in Gorlin syndrome (<2%)." (PMID 35843976, 2022). "A nonsense mutation in SUFU was discovered in a subset of patients with nevoid basal cell carcinomas (as in Gorlin Syndrome)." (PMID 34298625, 2021). "Mutations in PTCH1 are linked to 85% of cases of Gorlin Syndrome, however a subset of 5% of cases exhibit deleterious mutations in SUFU." (PMID 34298625, 2021). "Meningiomas resultant of Gorlin Syndrome or Familial multiple meningioma and childhood medulloblastomas have also been associated with SUFU mutations." (PMID 34298625, 2021). "Similar to PTCH1- and SUFU-associated MBSHH in Gorlin syndrome, patients in this study were typically diagnosed with MB during infancy." (PMID 31609649, 2020). "Aberrations in Hh pathway genes PTCH1, PTCH2, and SUFU are associated with nevoid basal cell carcinoma syndrome (NBCCS; also known as Gorlin syndrome), which predisposes patients to SHH-MB, basal cell carcinoma, and skeletal abnormalities." (PMID 29050204, 2017). "Recently, mutations in Suppressor of fused homolog (SUFU) or PTCH2 were reported in patients with Gorlin syndrome." (PMID 28915250, 2017). "Further investigation into this subset of patients has revealed that SUFU gene mutations may actually cause a distinct cutaneous cancer predisposition syndrome that, while extremely similar to, is different from Gorlin Syndrome." (PMID 34298625, 2021). "This case may be a rare germline SUFU mutation and a candidate for genetic counseling and surveillance for Gorlin syndrome." (PMID 32168907, 2020). "First, we investigated whether mutations were located in either the PTCH2 or SUFU genes, since both were reported as rare causative genes of Gorlin syndrome." (PMID 28915250, 2017). "Finally, mutations in SUFU have also been associated with Gorlin syndrome." (PMID 38439105, 2024). "Gorlin syndrome (nevoid basal cell carcinoma syndrome, NBCCS) is caused by heterozygous PTCH1 or SUFU germline mutations." (PMID 32168907, 2020). "Gorlin syndrome can also be caused by mutations in the patched 2 (PTCH2) gene and suppressor of fused (SUFU) gene as well." (PMID 40385857, 2025). "The most common BCC syndrome, Gorlin syndrome or basal cell nevus syndrome, is an autosomal dominant (AD) disorder most frequently associated with PTCH1 mutation, while PTCH2 and SUFU are less commonly implicated." (PMID 40290801, 2025). "Variants in SUFU and PTCH are responsible for the nevoid basal cell carcinoma syndrome (NBCCS) also known as Gorlin syndrome." (PMID 38741145, 2024). "SUFU is known to be a negative regulator of HH signaling that localizes to cilia tips and also has broad cancer relevance including a role in Gorlin syndrome." (PMID 37510333, 2023). "The main syndromic predisposition to medulloblastoma is Gorlin syndrome which is characterised by multiple skin basal cell carcinoma, macrocephaly and jaw cysts with two proven gene associations (PTCH1 and SUFU) accounting for ~ 70% of cases." (PMID 36961676, 2023).
Gorlin syndrome (continued). "Gorlin syndrome (GS), also known as nevoid basal cell carcinoma syndrome, is a neurocutaneous disorder linked to heterozygous mutations in PTCH1 (60–85%) and SUFU (<10%), two important genes of the Sonic Hedgehog signaling pathway." (PMID 35096710, 2021). "Gorlin syndrome, due to pathogenic mutations in PTCH1 and SUFU genes, is associated with increased risk of developing BCC." (PMID 33509032, 2021). "Gorlin syndrome is mainly caused by pathogenic germline variants in the tumour suppressor genes PTCH1 and SUFU, both regulatory genes in the hedgehog pathway." (PMID 31485359, 2019). "In fact, SUFU and PTCH2 mutations have been reported as another possible causative genes of Gorlin syndrome." (PMID 28915250, 2017). "Gorlin–Goltz syndrome, also known as nevoid basal cell carcinoma syndrome, is an autosomal dominant disease characterized by multisystemic developmental defects caused bypathogenic variants such as patched-1(PTCH1) gene variants and/or SUFU gene variants." (PMID 37564720, 2023). "Interestingly, germline mutations in SUFU, PTCH1, and GPR161 have been observed in heritable predisposition to MB, such as Gorlin syndrome." (PMID 37510333, 2023). "Our specific screen of GPR161 in our cohort of 27 PTCH1/SUFU pathogenic variant-negative patients with Gorlin syndrome found no pathogenic or likely pathogenic variants." (PMID 36961676, 2023). "We also screened 27 PTCH1/SUFU pathogenic variant-negative patients with Gorlin syndrome for GPR161 and found no suspicious variants." (PMID 36961676, 2023). "However, patients with mutated PTCH2 displayed milder phenotypes of Gorlin syndrome when compared against PTCH1 and SUFU-related diseases." (PMID 36937440, 2023). "The involvement of the Hh signaling pathway in Gorlin Syndrome has been established previously, however, it was not until a study in 2018 that the contributions of SUFU mutations to this syndrome were brought to light." (PMID 34298625, 2021). "Gorlin syndrome, or basal cell nevus syndrome, is a hereditary disease related to the mutations (more than 100 gene mutations have been reported) of patched 1, patched 2 and PTCH2, and SUFU genes, characterized by systemic and diverse developmental abnormalities and neoplastic lesions." (PMID 33809659, 2021). "Gorlin syndrome (MIM 109,400), a cancer predisposition syndrome related to a constitutional pathogenic variation (PV) of a gene in the Sonic Hedgehog pathway (PTCH1 or SUFU), is associated with a broad spectrum of benign and malignant tumors." (PMID 33860896, 2021). "In addition, mutations in rare causative genes other than PTCH1, such as PTCH2 and SUFU, have also been detected in individuals suffering from Gorlin syndrome." (PMID 26544948, 2015). "Patient 27 displayed a truncating germline SUFU variant discovered through clinical testing (c.1309_1310insT, p.Glu437Valfs*30, ACMG class 4, paternally inherited), causing Gorlin syndrome (also known as Basal cell nevus syndrome, autosomal dominant, MIM #109400)." (PMID 37046633, 2023). "Recently, gene alterations have been identified in the suppressor of fused homolog (SUFU) gene, present on chromosome 10q24.32, and in the PTCH2 gene, located on chromosome 1p34.1, in patients with Gorlin syndrome." (PMID 35843976, 2022). "Testing for PTCH1 and SUFU was negative, which reduced the likelihood of Gorlin syndrome or other known BCC syndromes." (PMID 40290801, 2025). "We did not identify GPR161 in 27 PTCH1/SUFU negative Gorlin syndrome families which represent all the 27/86-(31.4%) unexplained by known genes (59 were due to PTCH1/SUFU) meaning an unexplained population frequency far lower at 0.0021% (1 in 46,400)." (PMID 36961676, 2023). "Here, we uncover and functionally validate nine SUFU mutations from sequencing 58 sporadic human BCC tumor-normal pairs from patients with and without Basal Cell Nevus Syndrome (Gorlin’s Syndrome)." (PMID 28030567, 2016).
Gorlin syndrome (continued). "Recent findings suggest that haploinsufficiency for the two tumor suppressor genes PTCH (patched (Drosophila) homolog (nevoid basal cell carcinoma syndrome)) and SUFU (suppressor of fused homolog)-which are both active in this signaling pathway-is frequent in ERMS development." (PMID 21569414, 2011).
meningioma (32 papers, 2013 to 2025). A generally slow growing tumor attached to the dura mater. "Studies emphasise the importance of genetic screening for SUFU mutations in families with a history of meningiomas." (PMID 39568072, 2024). "Germline disruptions in SUFU are also thought to predispose to development of additional cancers such as basal cell carcinoma, gonadal tumors, and meningiomas." (PMID 36686824, 2022). "Across 850 meningiomas that underwent genomic analyses, SUFU mutations were identified in 23 patients and seen to co-occur with PTEN and ARID1A mutations." (PMID 36686824, 2022). "Suppressor of fused (SUFU) and patched 1 mutations can activate the SHH pathway, and somatic mutations of SUFU are present in 1% of sporadic meningiomas." (PMID 34679551, 2021). "Patients with SUFU mutations are more likely to develop meningiomas compared to PTCH1 or PTCH2 mutations even with the absence of PTCH mutation, which have been found in families with hereditary multiple meningiomas." (PMID 33801089, 2021). "A heterozygous SUFU missense mutation, NM_016169.4:c.367C>T p.(Arg123Cys), segregated with the meningiomas in the family, and functional analyses showed that the activity of the altered SUFU was significantly reduced." (PMID 34884862, 2021). "Additional studies in meningiomas identified a germline point mutation in SUFU present in a subset of patients." (PMID 34298625, 2021). "We present a family with a frameshift variant in the SUFU gene c.954del, p.Asn319Thrfs∗42 leading to meningiomas and multiple basal cell-carcinomas." (PMID 31485359, 2019). "Mutations in the Hedgehog family member SUFU are also found at low frequencies in sporadic meningiomas, though germline mutations are also present in familial meningioma." (PMID 31970090, 2019). "Aavikko and colleagues identified a germline SuFu mutation as the cause of multiple meningiomas in a single large Finnish family, suggesting that SuFu alterations predispose to meningiomas in addition to MBs." (PMID 31552081, 2019). "SUFU controls Gli(s) nuclear entry and thereby their transcriptional effects, and SUFU mutation in germline or somatic cells can lead to meningioma and chondrosarcoma." (PMID 30463396, 2018). "In addition, the meningiomas of 23 patients showed SUFU mutations, 18 in NF2-mutant (3.7%) and 5 in NF2-wt meningiomas (1.3%, p = 0.033)." (PMID 33087175, 2020). "Recent large-scale genome sequencing studies have revealed that approximately 5% of meningiomas contain activating mutations in the SHH pathway, particularly in the SUFU gene." (PMID 39568072, 2024). "Meningioma‐relevant mutations were present in 90/126 (71.4%) specimens including NF2, TRAF7, KLF4, SMO, AKT1,TERT promotor, ARID,SUFU, and PIK3CA mutations in similar frequencies compared to previous studies." (PMID 35213082, 2022). "Aberrant signaling in the sonic hedgehog (SHH) pathway caused by mutations in PTCH1, PTCH2, and SUFU genes, located at 9q22.32, 1p34.1, and 10q24.32, respectively, with PTCH1 being the most common, increases the risk of meningioma development." (PMID 33801089, 2021). "We also observed an enrichment in alterations in CDKN2A/B, KDM6A, ARID1A, PTEN, FBXW7, and SUFU in comparison with NF2-wt meningiomas." (PMID 33087175, 2020). "All four cases, three of whom had a history on meningioma, carry a 1-bp deletion (c.954del) in SUFU resulting in a frameshift and a premature stop codon (p.Asn319Thrfs∗42)." (PMID 31485359, 2019). "For people with only meningiomas, germline testing may also include SMARCE1 and SUFU, which are rare causes of predisposition to non-NF2-related meningiomas." (PMID 41284083, 2025). "However, while meningiomas with mutations in SMO and SUFU are more commonly associated with lower-grade histology, they have been found to have higher rates of recurrence, possibly related to bony invasion as evidenced by hyperostosis." (PMID 37010677, 2023).
meningioma (continued). "Meningiomas in the midline anterior skull base, along the olfactory groove or planum sphenoidale, typically harbor an underlying somatic mutation in one of the molecules involved in Hedgehog signaling, including SMO or SUFU." (PMID 37010677, 2023). "Meningiomas harboring recurrent somatic SMO mutations are part of a larger group of samples that exhibit activation of the Hedgehog (Hh) signaling pathway, which also includes cases with somatic biallelic loss of SUFU or PRKAR1AA17D mutation." (PMID 37805627, 2023). "Changes in SUFU lead to dysregulation of the hedgehog (Hh) signaling pathway, the activation of which has been shown to play a critical role in meningioma growth and development, with 72% of Hh signaling pathway genes being differentially expressed in meningiomas compared to normal tissue." (PMID 36686824, 2022). "Among the non-NF2 mutant meningioma subgroup, mutations in SMO and SUFU were identified." (PMID 36010600, 2022). "Genetic testing using panel-based NGS of tissue from the meningioma showed LOH in the SUFU gene." (PMID 31485359, 2019). "The LOH of SUFU in the meningioma in our study (case III) shows that it is highly likely that the development of meningioma in this subject was due to the inherited SUFU pathogenic variant, consistent with the two-hit hypothesis." (PMID 31485359, 2019). "As there was no LOH in the meningioma of case I, it is uncertain if the development of this meningioma was caused by the pathogenic SUFU variant, but a LOF mutation on the other allele could not be excluded." (PMID 31485359, 2019). "Interestingly, these mutations did not overlap with another study investigating SUFU mutations in multiple meningioma." (PMID 28030567, 2016). "Additional common pathological relevant genes of meningiomas, including AKT1 (n = 3; 8%), CDKN2A (n = 2; 5%), SMO (n = 0; 0%), SUFU (n = 0; 0%), POLR2A (n = 6; 16%), TRAF7 (n = 1; 3%), and SMARCB1 (n = 2; 5%), were observed as well." (PMID 34778063, 2021). "Of note, other common pathological relevant genes of meningiomas, including AKT1 (n = 3; 8%), CDKN2A (n = 2; 5%), SMO (n = 0; 0%), SUFU (n = 0; 0%), POLR2A (n = 6; 16%), TRAF7 (n = 1; 3%), and SMARCB1 (n = 2; 5%), were detected as well." (PMID 34778063, 2021). "Their study presented five family members with meningiomas and LOH of the SUFU gene was detected in all the meningiomas." (PMID 31485359, 2019). "Of the two genetically tested meningiomas, one had LOH of the SUFU gene." (PMID 31485359, 2019). "In meningiomas, the absence of trimethylation of H3K27 (H3K27me3) has been shown to be associated with more aggressive growth of tumor, as well as NF2 and SUFU mutations, allowing us to further stratify grade 1 and 2 tumors according to the 2016 WHO classification system." (PMID 36686824, 2022). "In addition, there are more rare germline mutations in meningiomas including mutations of Switch/Sucrose non-Fermentable Family (SWI/SNF)-Related, Matrix-Associated, Actin-Dependent Regulator of Chromatin, Subfamily B, Member 1 (SMARCB1), SMARCE1, BAP1, and SUFU genes." (PMID 38001599, 2023).
glioma (11 papers, 2013 to 2026). A benign or malignant brain and spinal cord tumor that arises from glial cells (astrocytes, oligodendrocytes, ependymal cells). "SMO mediates a downstream signal transduction, including suppressor of fused homolog (SUFU), which lastly determines the activation of the glioma-associated oncogenes homologs (GLI) family of transcription factors." (PMID 35775005, 2022). "To examine the role of SuFu in gliomas, we induced its upregulation and downregulation in GB18 and GB27 CSCs." (PMID 36091108, 2022). "This work identifies SuFu as a new molecular player in glioma cell migration and a promising target to develop blocking agents to decrease GB dissemination." (PMID 36091108, 2022). "For this reason, and to investigate SuFu function in different grade glioma tumors, we analyzed its expression in three cohorts (N = 1,759) and established the correlation with migration and stemness patterns." (PMID 36091108, 2022). "Although the dichotomy between migration and proliferation has generated intense controversy in glioma field, here, we found that both processes present mutually exclusive behaviors when we modulate SuFu expression." (PMID 36091108, 2022). "For this reason, we decided to focus our study on elucidating SuFu’s role in glioma tumors." (PMID 36091108, 2022). "In addition, although they observed that SuFu ectopic expression restrains cell proliferation and invasion, they performed their experiments in established glioma cell lines with compromised stem properties, whereas our assays present a more realistic 3D model." (PMID 36091108, 2022). "In glioma LN229 and U251 cells, curcumin reversed the EMT process induced by γ-irradiation via the suppression of GLI1 and the upregulation of Suppressor of Fused Homolog (SUFU), as well as by suppressing the HH signaling pathway both in vitro and in vivo." (PMID 31547193, 2019).
basal cell carcinoma (10 papers, 2014 to 2025). A carcinoma involving the basal cells. "Somatic SUFU mutations have also been found in various cancers, including sporadic basal cell carcinomas, where they have been shown to inappropriately enable GLI1-driven transcription." (PMID 35831023, 2022).